MIR4256 (microRNA 4256)
Synonyms: hsa-mir-4256
Gene: MicroRNA gene on chromosome 1 (112,461,770 to 112,461,833, reverse strand). Ensembl gene ENSG00000283296.
Diseases named in the same sentence as MIR4256 in open-access papers:
MIR4256 is named in the same sentence as 2 diseases in open-access papers, as found by Europe PMC text mining. Sharing a sentence is not in itself a finding about the gene and the disease.
MIR4256 shares sentences with these, for which no sentence is quoted: psychiatric disorder (1 paper); schizophrenia (1).